BACH1 (BACH transcriptional regulator 1)
Diseases named in the same sentence as BACH1 in open-access papers (continued):
Sharing a sentence is not in itself a finding about the gene and the disease.
breast carcinoma (continued). "Remarkably, stratifying breast cancer patients by high RKIP (PEBP1) and low BACH1 expression or vice versa reveals a striking inverse association of RKIP with BACH1 and the motility-related genes in ~60% of patients." (PMID 33973518, 2021). "Direct target genes of BACH1 in breast cancer include many of those involved in the function of mitochondria, including oxidative phosphorylation." (PMID 34339740, 2021). "It was observed that enhancing the reliance of breast cancer cells to mitochondrial functions by modulating the transcription factor BACH1 using hemin which initiates degradation of BACH1, sensitizes the cancer cells to metformin." (PMID 33926547, 2021). "In a previous report, hemin treatment to breast cancer cells and the mice bearing breast tumors exhibited substantially reduced BACH1 levels with unnoticeable toxicity, suggesting hemin as a potentially non-toxic BACH1-specific drug for tumors." (PMID 33809182, 2021). "BACH1 has been established as a major regulator of breast cancer bone metastasis and was postulated as a potential novel therapeutic candidate for cancer treatment." (PMID 32132179, 2020). "BACH1 has been placed downstream of the Raf kinase inhibitory protein, a tumor suppressor gene shown to inhibit invasion and bone metastasis in a breast cancer xenograft mouse model." (PMID 32132179, 2020). "Mutation in the BRCT domain disturbs the proper connection between BRCA1 and BACH1, which results in delayed entry into the S phase of the cell cycle, defective DNA repair, and breast cancer development." (PMID 33013205, 2020). "Ectopic expression of BACH1 in breast cancer cells promotes malignancy and metastasis, whereas its knockdown suppresses these processes." (PMID 32132179, 2020). "Accumulating evidence indicates the involvement of several transcription factors, Runx-2 and Bach1, in breast cancer metastasis to bone." (PMID 33081224, 2020). "Green points (each point represents a single cell) correspond to untreated breast cancer cells, while magenta points correspond to breast cancer cells after shBACH1 treatment (BACH1 knockdown)." (PMID 30155271, 2018). "BACH1 transcriptionally adjust several involved genes in the osteolytic metastasis of breast cancer, and more significantly, it promotes the invasiveness and metastasis of breast cancer cells." (PMID 28000777, 2016). "Here we showed that let-7a overexpression induced HMOX1 and repressed BACH1 also in breast cancer and melanoma cell lines." (PMID 25669981, 2015). "These correlations have the potential to suggest a functional profiling of the involvement of the BACH1 gene in the development of breast cancer." (PMID 24137204, 2013). "Experimental validation using a xenograft mouse model confirmed that RKIP and let-7 suppress BACH1 and HMGA2 expression and showed that BACH1 promotes invasion, intravasation, and bone metastasis of breast cancer cells." (PMID 22482058, 2012). "We sought to carry out mutation analysis of FANCD2, BRIP1/BACH1, LMO4 and SFN in a large number of non-BRCA1/2 breast cancer families." (PMID 16280053, 2005). "Generally speaking, Bach1 has a key regulatory role in the production of reactive oxygen species, cell cycle, heme homeostasis, hematopoiesis, and immunity and has been shown to suppress ischemic angiogenesis and promote breast cancer metastasis." (PMID 39905004, 2025). "Targeting BACH1 could normalise glycolysis and prevent breast cancer cell metastasis, while overexpression of BACH1 could enhance glycolysis and promote breast cancer cell metastasis." (PMID 39991762, 2025). "The redox-sensitive transcription factor BACH1 facilitates breast cancer metastasis, but its molecular upstream control remains unclear." (PMID 40263598, 2025).
breast carcinoma (continued). "We then investigated SDCBP and BACH1 expression levels in several human breast cancer cell lines." (PMID 40263598, 2025). "Furthermore, the expression levels of BACH1 or MCT1 were analyzed using the following clinical variables: breast cancer subtypes, tumor stages, tumor grade, and tumor size." (PMID 40710214, 2025). "A heme-binding transcription factor, BTB and CNC homology 1 (BACH1), has been shown to promote breast cancer metastasis, particularly in triple-negative breast cancer (TNBC), which is one of the most aggressive and lethal subtypes of breast cancer because of the lack of targeted therapy." (PMID 40710214, 2025). "BACH1 also regulates metabolic networks of cancer cells to support breast cancer metastasis." (PMID 40710214, 2025). "In breast cancer, BACH1 results in drug resistance related to mitochondrial metabolism." (PMID 38321558, 2024). "BTB domain and CNC homolog 1 (BACH1), a heme-binding protein from the basic leucine zipper factor family, plays multifaceted roles in oxidative stress regulation, tumor metastasis, and mitochondrial metabolism in breast cancer." (PMID 38838145, 2024). "Notably, BACH1−/− breast cancer cells had significantly reduced metastatic potential in Ctrl diet groups, which is consistent with previous studies showing BACH1 is a pro-metastatic protein." (PMID 38838145, 2024). "Thus, targeted inhibition of BACH1, as a promising strategy, increases the sensitivity to chemotherapy drugs that suppress mitochondrial metabolism in breast cancer and potentially other cancers." (PMID 38321558, 2024). "In this approach, tumor cells are transfected with specific siRNAs that downregulate the expression of BACH1 in a dose-dependent manner, thereby repressing the migration and proliferation of breast cancer cells, leading to cell cycle arrest and promoting apoptosis." (PMID 38321558, 2024). "Furthermore, in breast cancer, BACH1 can inhibit the expression of electron transport chain-related genes." (PMID 37946265, 2023). "BACH1 is a transcription factor having a role in tumor relapse and metastasis in breast cancer." (PMID 36873936, 2023). "BACH-1 regulates the migration and invasiveness of breast carcinoma cells." (PMID 35884446, 2022). "Meanwhile, through regulating the transcription of electron transport chain (ETC) genes, BACH1 reduces glucose usage in the tricarboxylic cycle in breast cancer cells, which may partly explain the Warburg effect." (PMID 35651942, 2022). "Moreover, mice xenografted with BACH1-enriched breast cancer cells or TNBC patient-derived xenograft (PDX) mice showed significantly tumor suppression when mice were injected with hemin to reduce BACH1 levels and metformin." (PMID 33809182, 2021). "In contrast, expression of BACH1 was high in all breast cancer cell lines." (PMID 34262028, 2021). "Moreover, the mitochondrial gene targets of RKIP positively correlated with RKIP, while negatively correlating with BACH1 gene expression in breast cancer patients." (PMID 33973518, 2021). "Inspired by the potential involvement of several transcription factors such as Runx-2 and Bach1 in breast cancer bone metastasis, we searched for an additional transcription factor(s), which is associated with augmented proliferation of 4T1.3 clone in a bone cavity." (PMID 33081224, 2020). "Similarly, it was shown that BACH1 promotes the metastasis of breast cancer through different molecular mechanisms and its stabilization in lung adenocarcinoma is associated with increased metastatic dissemination and poor survival." (PMID 32132179, 2020). "Another miRNA, miR-142-3p, belonging to the miR-142 family, might be related to the development of various types of malignancies, especially breast cancer, by targeting various mRNAs, including Bach1, which is highly active in cancerous cells." (PMID 33194751, 2020).
breast carcinoma (continued). "Further studies have also indicated that overexpression of miR-142-3p in breast malignancies resulted in the downregulation of Bach-1, making it likely that miR-142-3p could be a target in breast cancer therapy." (PMID 33194751, 2020). "Along with the MMP1 inhibition by the RKIP/let-7/BACH1 axis in breast cancer cells, RKIP may exert inhibitory activities on MMPs expression through alternative signaling axes." (PMID 30149591, 2018). "Endogenous MafK and Bach1 also suppressed HO-1 in breast cancer cells." (PMID 23737527, 2013). "The shape of the funnel plot for the correlation between the BACH1 919Ser polymorphism and breast cancer risk did not indicate any marked asymmetry." (PMID 24137204, 2013). "By contrast, certain other studies have suggested that the BACH1 Pro919Ser polymorphism is not correlated with an increased risk of breast cancer." (PMID 24137204, 2013). "Similarly, high mRNA expression of the BRCA1-interacting protein BACH1/Brip1 has been found in aggressive breast cancers." (PMID 19002265, 2008). "Our results further indicate that BACH1 Ser919 is not a breast cancer predisposition allele in the Finnish population." (PMID 16430786, 2006). "Previously, two BACH1 germ line missense mutations have been identified in early-onset breast cancer patients with and without family history of breast and ovarian cancer." (PMID 16430786, 2006). "Our results suggest that the BACH1 Ser919 is not a breast cancer predisposition allele in the Finnish study population." (PMID 16430786, 2006). "BACH1 (BRCA1-associated C-terminal helicase 1; also known as BRCA1-interacting protein 1, BRIP1) is a helicase protein that interacts in vivo with BRCA1, the protein product of one of the major genes for hereditary predisposition to breast cancer." (PMID 16430786, 2006). "We therefore hypothesized that germline mutations in the BRCA1-interacting genes, FANCD2, BRIP1/BACH1, LMO4 and SFN, may account for some non-BRCA1/2 multiple-case breast cancer families." (PMID 16280053, 2005). "We hypothesized that germline mutations in FANCD2, BRIP1/BACH1, LMO4 and SFN may account for some of the unexplained multiple-case breast cancer families." (PMID 16280053, 2005). "Therefore, tumoral BACH1 expression predicts a worse outcome for patients with breast cancer." (PMID 40710214, 2025). "Thus, RKIP and BACH1 create a mutually suppressive regulatory loop in breast cancer cells." (PMID 33809182, 2021). "Thus, Bach1 function differs between different cancer cell types, even within the same cell type (e.g., breast cancer cells), and Bach1 may have a different effect on cancer cell growth and cancer metastasis." (PMID 30370001, 2018). "Further subgroup analyses indicated that there were significant correlations between the BACH1 919Ser polymorphism and a decreased risk of breast cancer in postmenopausal females, females with a family history of breast cancer and females without BRCA1/2 mutations." (PMID 24137204, 2013). "BACH1 (BRCA1-associated C-terminal helicase 1, also known as BRCA1-interacting protein 1, BRIP1; GenBank: NM_032043) belongs to a DEAH helicase family and interacts in vivo with BRCA1, the protein product of one of the two major genes for hereditary breast cancer susceptibility." (PMID 16430786, 2006). "In breast cancer, SNHG5 activates a metabolic reprogramming program by regulating BACH1 through miR-299, thereby upregulating glycolytic enzymes such as HK2 and PFK1, and promoting proliferation via enhanced aerobic glycolysis." (PMID 41550840, 2026). "Among the genes altered by RKIP modulation, and besides the ones present in our transcriptomic analysis, we also explored BACH1 expression, given its reported feedback loop with RKIP in breast cancer." (PMID 40720248, 2025).
breast carcinoma (continued). "Western blot analyses showed high SDCBP and BACH1 protein expressions in TNBC cell lines (e.g., MDA-MB-231, MDA-MB-468, and Hs578T), while lower levels were found in luminal A breast cancer cell lines (e.g., MCF-7 and T47D) (Fig. EV1C,D)." (PMID 40263598, 2025). "Akin to BACH1, MCT1 is a known prognosis marker for breast cancer, and the inhibition of MCT1 using AZD3965 is currently under investigation in clinical trials to be applied as a targeted cancer therapy." (PMID 40710214, 2025). "BACH1, a CNC-bZip transcription factor, regulates iron-related genes and promotes breast cancer metastasis." (PMID 40963614, 2025). "BACH1 is repressed by RKIP, which targets let-7, thereby inhibiting breast cancer bone metastasis by downregulating the expression of BMS genes, including MMP1, OPN, and CXCR4." (PMID 38321558, 2024). "MafG accelerates cell proliferation and inhibits cell apoptosis in lung adenocarcinoma, while MafF promotes tumor invasion through heterodimerizing with Bach1 and activating the IL11/STAT3 pathway in breast cancer." (PMID 37491302, 2023). "In TCGA breast cancer samples, we observed that ESR1 correlated positively with RKIP (ρ = 0.11), but negatively with BACH1 (ρ = −0.29)." (PMID 37963558, 2023). "RKIP and BACH1 have been reported as mutually inhibitory players in breast cancer; while RKIP is anti-metastatic, BACH1 is pro-metastatic." (PMID 37963558, 2023). "Anticorrelation between BACH1 and RKIP in the TCGA breast cancer dataset up to a BACH1 level echoes our findings in MB231 cells." (PMID 37231268, 2023). "Recent reports have identified a mutually inhibitory feedback loop between the Raf kinase inhibitor protein (RKIP) and BTB and CNC homology 1 (BACH1) in the regulation of EMT and metastasis in breast cancer." (PMID 37963558, 2023). "Next, we focused on breast cancer, given the earlier observations about the mutually antagonistic roles of RKIP and BACH1 in breast cancer." (PMID 37963558, 2023). "In breast cancer (BRCA) tissues, the BACH1 expression was positively related to the infiltrating levels of CD8/CD4+ T cells, neutrophils, macrophages, and myeloid dendritic cells; but negatively related to that of B cells." (PMID 35651942, 2022). "They include SNAIL and BACH1 whose direct binding to the RKIP promoter suppresses RKIP transcription and expression in prostate and breast cancer." (PMID 36291854, 2022). "BACH1 also directly enhances the expression of genes involved in cell motility and invasiveness, including ROCK1 in breast cancer." (PMID 34339740, 2021). "The heterodimer of BACH1 and its partner MAFF induce the expression of IL-11 in breast cancer cells to promote invasiveness." (PMID 34339740, 2021). "Bach1 is a transcriptional regulator that activates expression of glycolytic genes and represses transcription of the TCA cycle and ETC genes in lung and breast cancer cells." (PMID 34807950, 2021). "The decrease in BTB and CNC homology 1(BACH1), a hemin-binding transcription factor, can promote the expression of the electron transport chain(ETC) genes to increase the sensitivity of breast cancer to metformin." (PMID 33816265, 2021). "In breast cancer cells, a metastasis suppressor, Ras Kinase Inhibitory Protein (RKIP), indirectly suppresses BACH1 expression through a regulatory cascade that includes MAP Kinase, LIN28, and its downstream let-7 miRNA." (PMID 33809182, 2021). "The present meta-analysis suggested that the BACH1 919Ser polymorphism may decrease the risk of breast cancer among Caucasian populations, particularly in postmenopausal females with a family history of breast cancer and without BRCA1/2 mutations." (PMID 24137204, 2013). "The human BACH1 gene is located on chromosome 17q22, distal to the BRCA1 gene located at 17q21, a region that is frequently altered in breast cancer." (PMID 24137204, 2013).
breast carcinoma (continued). "Real-time quantitative polymerase chain reaction (qPCR) analyses revealed that the mRNA expression levels of SDCBP, but not those of BACH1, correlated with the protein expression levels in the breast cancer cell lines (Fig. EV1D,E)." (PMID 40263598, 2025). "TBE53 (but not TBE31) reduces breast cancer cell migration and invasion in a BACH1-dependent manner." (PMID 38321558, 2024). "In TCGA breast cancer samples and in other TCGA cancer types, ssGSEA scores of RKIP pathway metastasis signature (RPMS) correlated negatively with RKIP, while those of BACH1 pathway metastasis signature (BPMS) correlated positively with BACH1." (PMID 37963558, 2023). "Unexpectedly, engineered MDA-MB-231 metastatic human breast cancer cells become more, then less and then more invasive as we tune BACH1 levels up, irrespective of the native BACH1." (PMID 37231268, 2023). "These suggest that cellular levels of BACH1 are also tightly regulated in human breast cancer cells through a negative feedback loop." (PMID 33809182, 2021). "BACH1 has been reported to promote the expression of CXCR4 in colorectal and breast cancers." (PMID 34339740, 2021). "The anti-tumorigenic effect of let-7 by targeting both HMGA2 and BACH1 is especially effective in abrogating bone metastasis in a breast cancer model where the two proteins share some but not all of the same target genes." (PMID 25546138, 2014). "In conclusion, the present meta-analysis indicated that the BACH1 919Ser polymorphism may decrease the risk of breast cancer among Caucasian populations, particularly in postmenopausal females with a family history of breast cancer and without BRCA1/2 mutations." (PMID 24137204, 2013). "The BACH1 gene was screened for germ line alterations among probands from 43 Finnish BRCA1/2 negative breast cancer families." (PMID 16430786, 2006). "Finally, survival analysis of breast cancer patients indicated that expression of both MAFF and BACH1 or MAFF, BACH1, and IL11 was significantly correlated with distant metastasis-free survival, further strengthening the prognostic significance of MAFF/IL11 pathways." (PMID 34262028, 2021). "Further studies in breast cancer models revealed that RKIP may also prevent tumor cell invasion and metastasis indirectly, by negative regulation of critical prometastatic factors downstream of let-7, including high mobility group AT-hook 2 (HMGA2) and BACH1." (PMID 30149591, 2018). "In contrast to Snail (SNAI1), BACH1 expression is significantly inversely correlated with RKIP expression in the TCGA breast cancer patient database, suggesting that BACH1 may be the main negative regulator of RKIP in breast cancer." (PMID 30181452, 2018). "In breast cancers, inhibition of MAPK suppresses invasion and metastasis in part by increasing let-7 expression, which leads to suppression of the let-7 targets High-mobility group AT-hook 2 (HMGA2) and BTB-and CNC homology 1 leucine zipper transcription factor (BACH1)." (PMID 25546138, 2014).